ALB (albumin)
Diseases named in the same sentence as ALB in open-access papers (continued):
Sharing a sentence is not in itself a finding about the gene and the disease.
liver cancer (continued). "We decided to continue the study with the HepG2 line because they expressed liver-specific and hepatic cancer stem cells markers such as CD133, alpha fetoprotein, GAPDH, and albumin." (PMID 34577545, 2021). "Forty-four (69.8%) patients were Barcelona Clinic Liver Cancer classification (BCLC) C, and the modified albumin-bilirubin (mALBI) classifications were 1 (n = 18), 2a (n = 20) and 2b (n = 25)." (PMID 32756366, 2020). "The levels of ALB and GGT before operation are potential biomarkers to predict the prognosis of patients with liver cancer undergoing radical resection." (PMID 32963562, 2020). "We examined the liver cancer stem cell or progenitor markers (AFP, CD133, EPCAM, and KRT19), and hepatocyte terminal differentiation markers (ALB, G6PC, CYP3A4, and HNF4A) in subgroup of patients with different SOX signature scores." (PMID 31462277, 2019). "Hence, low albumin levels may contribute to liver cancer progression." (PMID 30521023, 2018). "Genes specifically expressed in liver cells [i.e., albumin (ALB) and tyrosine aminotransferase (TAT)] and a gene expressed in liver cancer/immature cells [i.e., α-fetoprotein (AFP)] were used as endogenous control genes." (PMID 29065189, 2017). "Compared with controls, liver cancer patients showed a higher percentage of HBsAg positive (65 vs. 25%), anti-HCV positive (9 vs. 3%), and had higher plasma AFB1-albumin adduct levels (30 vs. 20% in the 5th quintile)." (PMID 25337902, 2014). "The univariate logistic regression model indicated the following prognostic factors: diagnosis of liver cancer, cognitive status, edema, jaundice, ECOG score, ascites, WBC, platelet, BUN, creatinine, SGOP, SGPT, albumin level and respiratory rate (P < 0.05)." (PMID 19785768, 2009). "Notably, PDX models generated with Liver ECM displayed higher expression of liver cancer-specific markers AFP and ALB, compared to PDX models with Matrigel, indicating enhanced tumor progression by Liver ECM." (PMID 40852642, 2025). "In addition to TM4SF5-positive liver tissue from patients with HCC showing obvious ALB levels, patients with liver cancer (LIHC) from TCGA datasets showed a positive correlation between TM4SF5 and hepatic ALB levels." (PMID 40186033, 2025). "RDW (HR = 1.2524; 95% CI 1.0786–1.4542, p = 0.0032) and total bilirubin (HR = 1.2121; 95% CI 1.0155–1.4468, p = 0.031) remained significantly associated with survival after adjusting for the Child–Pugh score, Barcelona Clinic Liver Cancer (BCLC) stage, number of lesions, treatment, albumin, and ALP." (PMID 38541117, 2024). "Furthermore, the following four covariates related to objective response were taken into account: age, sex, albumin-bilirubin (ALBI) grade and Barcelona clinic liver cancer (BCLC) stage." (PMID 31991869, 2020). "Postoperative mortality of patients with HCC was influenced by the following risk factors: DPHCC (P = 0.023), CK19 positivity (P = 0.006), Barcelona Clinic Liver Cancer (BCLC) stage C (P = 0.027), multiple nodules (P = 0.024), serum albumin <35 g/L (P = 0.046) and CA19-9 >37 ng/ml (P = 0.017)." (PMID 32231746, 2020). "Univariate analysis shows that in addition to albumin expression (P = 0.03), tumor, node and metastasis (TNM) staging (P = 0.007) and Barcelona clinic liver cancer (BCLC) staging (P = 0.002), the RGC classification was a significant indicator for OS (P = 9.4 × 10−6) in the Singapore cohort." (PMID 29117471, 2018). "Furthermore, although expression of liver or liver cancer markers differs between primary HCC cells, eight cultures of primary HCC cells exhibited albumin and HepPar-1 expression in the cytosol as well as AFP and albumin mRNA expression." (PMID 29801504, 2018). "Non-cardio-selective beta-blockers, ascites, albumin levels, total number of platelets, INR values, and levels of AFP were independent risk factors for HCC occurrence in cirrhotic patients with no history of liver cancer." (PMID 40095031, 2025).
liver cancer (continued). "The 2022 updated Barcelona Clinic Liver Cancer strategy for prognosis prediction and treatment recommendation for HCC suggested evaluating prognosis according to the tumor burden and cancer-related symptoms, and defined by the AFP, albumin-bilirubin score, Child-Pugh, and MELD scores." (PMID 37239939, 2023). "Barcelona Clinic Liver Cancer (BCLC) stage and alpha fetoprotein (AFP), aspartate aminotransferase (AST), gamma-glutamyl transferase (GGT), lactate dehydrogenase (LDH), alkaline phosphatase (ALP), and albumin (ALB) levels differed between the SIRI < 1.05 and SIRI ≥ 1.05 groups." (PMID 28430597, 2017). "Interestingly, while among those HBsAg negative HCC patients, Barcelona Clinic Liver Cancer (BCLC) stage, INR value and Albumin (ALB) value, but not AFP value, were the independent risk factors affecting postoperative survival time." (PMID 26784252, 2016). "In the univariate analysis, significant differences were observed in treatment line, performance status, Child–Pugh score, albumin-bilirubin (ALBI) score, modified ALBI (mALBI) grade, Barcelona Clinic Liver Cancer (BCLC) stage, and presence/absence of macrovascular invasion." (PMID 39289234, 2024). "The results of scRNA-seq revealed that when some liver cancer patients were not treated with sorafenib, the JUN family genes in some liver cancer cells were over-activated, and the HIF pathway was metabolized through the high interaction between ALB and FcRn." (PMID 34421602, 2021). "Even though recent studies have found that modified branched-chain DNA probes for albumin mRNA (used for in situ detection of albumin expression) have a detection rate of 99% for CCA and 100% for liver cancer, these are not detected exclusively in CCA, not even in early stages." (PMID 31569444, 2019). "Additionally, as human serum albumin (HSA) nanoparticles are becoming a non-toxic drug delivery system, and thus their inclusion for drug nanoencapsulation was also addressed in vitro (human liver cancer HepG2 cells) and in vivo (H22 tumor-bearing mice)." (PMID 34540888, 2021).
lymphopenia (138 papers, 2010 to 2026). Reduction in the number of lymphocytes. "Low albumin and hemoglobin levels reflect protein-energy malnutrition and reduced oxygen-carrying capacity, while lymphopenia and thrombocytosis are linked to immune suppression and tumor-promoting inflammation." (PMID 40528068, 2025). "In our study, we found that lymphopenia, along with low levels of albumin and hemoglobin, was strongly linked to mortality in patients treated with remdesivir." (PMID 38610602, 2024). "A study revealed that PJP was independently associated with lymphopenia, antilymphocyte monoclonal antibodies, high-dose steroid treatment, low albumin, and low body mass index." (PMID 39717043, 2024). "Patients with high concentration of NT-proBNP, troponin, CRP, lactates, ferritin, D-dimers, and creatinine and a lower concentration of PLT, albumin, leukocytes, lymphopenia, and hyponatremia are at risk for immunoglobulin treatment resistance." (PMID 35948653, 2022). "Elevated CRP and low albumin levels denote a catabolic, pro-inflammatory state that may predispose to procedural complications, while lymphopenia reflects immune suppression and increased infection risk." (PMID 41470144, 2025). "Moreover, being underweight, which was observed in 16.3% of our patients, might reduce serum albumin levels and cause lymphocytopenia." (PMID 36614896, 2022). "According to the table, lymphopenia, decreased albumin, increased globulin, and the A: G ratio decreased significantly with additional treatment time, and the low number of cats outlined the normal range values." (PMID 41360910, 2025). "FIV-infected cats exhibited lymphopenia, thrombocytosis, hyperglobulinemia, and reduced albumin/globulin ratios." (PMID 40877940, 2025). "The CONUT score reflects albumin depletion, lymphopenia, and hypocholesterolemia—hallmarks of pancreatic cancer malnutrition—whereas NRS-2002 integrates systemic disease burden." (PMID 41178947, 2025). "For mortality, adverse outcomes were associated with life support limitations, the need for ventilatory support (particularly IMV) 14 days after the initial remdesivir dose, lymphopenia, low albumin and hemoglobin levels, flu and/or coinfection, and cough." (PMID 38610602, 2024). "Factors associated with worse outcomes in terms of mortality included limitations in life support, ventilatory support needs, lymphopenia, low albumin and hemoglobin levels, flu and/or coinfection, and cough." (PMID 38610602, 2024). "In this study, A. veronii adversely affected the hematological parameters in the AV group, where significant declines in RBCs, HCT, Hgb, total protein, albumin, and globulin as well as leukopenia, neutropenia, and lymphopenia were observed." (PMID 37438674, 2023). "In most of the studies conducted for SARS-CoV-2 infection, lymphopenia, low serum albumin levels, and increased LDH, AST, ALT, creatine phosphokinase-MB (CK-MB), and troponin levels are observed." (PMID 36788868, 2023). "Lung V5, baseline ALC, during-CRT ALC, and albumin nadir were independent predictors of delayed lymphopenia." (PMID 36059659, 2022). "In terms of blood markers, lower baseline/during-CRT albumin, ALC, and hemoglobin were significantly associated with delayed lymphopenia." (PMID 36059659, 2022). "In the present study, ALC (baseline/during-CRT) and albumin (during-CRT) nadirs were independent predictors of delayed lymphopenia." (PMID 36059659, 2022). "The group with cardiac dysfunction or shock symptoms had significantly elevated markers of inflammation, granulocytosis, and significant lymphopenia, low levels of albumin and sodium, and significantly higher levels of NT-proBNP." (PMID 35948653, 2022). "On multivariable logistic regression models, lung V5, baseline ALC, during-CRT ALC, and albumin nadir were significant predictors for delayed lymphopenia." (PMID 36059659, 2022).
lymphopenia (continued). "In controls, Lymphopenia (n=436, 94.1%, p=0.05), AST (n=59, 12%, p=0.008) and Albumin (n=40, 10.7%, p=0.02) have shown an association with increased mortality." (PMID 35350203, 2022). "By univariate analysis, age, lymphopenia, d-dimer greater than 1 μg/mL, albumin less than 30 g/L on admission and corticosteroid treatment were associated with 28-day mortality." (PMID 36443688, 2022). "In univariate analysis, older age, comorbidity, lymphopenia, high levels of CRP, ESR, lactate, estimated glomerular filtration rate (e-GFR), low levels of albumin, and fewer vaccination doses are all associated with the severity of Omicron infection." (PMID 36146487, 2022). "Lymphopenia, low SpO2 and albumin levels, elevated serum LDH, ferritin, urea, and CRP levels were found to be significantly correlated with severity CT score (P<0.0001)." (PMID 35802733, 2022). "Lung V5, ALC (baseline, nadir during CRT), and albumin nadir during CRT were independent predictors of delayed lymphopenia." (PMID 36059659, 2022). "Elderly patients showed a greater prevalence of positive laboratory tests, such as leukocytosis, lymphopenia, decreased platelet count, hemoglobinemia, lower albumin, increased D-D-dimer, and prolonged prothrombin times." (PMID 35087843, 2021). "Serum albumin level [3.4 g/dl (2.9–3.8) vs. 3.8 g/dl (3.5–4.1), p = 0.002] and presence of lymphopenia rate (< 800 /μl) (90.9% vs. 66.3% p = 0.018) were significantly lower in these patients." (PMID 33740915, 2021). "The most frequent laboratory findings are an increase in inflammatory indices (CRP, procalcitonin, ferritin, ERS, IL-6), cardiac markers (BNP, troponin), and D-dimer levels, leukocytosis (with lymphopenia), and reduced albumin levels." (PMID 34422717, 2021). "The most common laboratory abnormalities observed in this study were decreased albumin, lymphopenia, increased d-dimer, and elevated lactate dehydrogenase." (PMID 33542448, 2021). "• Most common: Increased levels of CRP (59.4%) and lactate dehydrogenase (LDH) (51.7%), low levels of albumin (58.6%) and lymphopenia (47.7%)." (PMID 34760713, 2021). "In a previous study, lymphopenia (31.4%), increased D-dimer (38.1%), depressed albumin (36.2%), elevated LDH (41.0%), and a high level of CRP (79.0%) were common among elderly patients with Covid-19." (PMID 34809556, 2021). "The most significant findings were lymphocytopenia (62.7%, 95% CI 47.1–78.3%), decreased albumin (60.6%, 95% CI 0–100%) and increased lactate dehydrogenase (LDH) (57.4%, 95% CI 31.7–83.1%)." (PMID 32668763, 2020). "Fever (88.7%), cough (64.2%), fatigue (34%), and abnormal laboratory indicators, including lymphopenia, reduced albumin, albumin/globulin (A/G), and elevated C-reactive protein (CRP), were mainly observed." (PMID 32746805, 2020). "Patients with PJP had lower body mass index (21 vs. 25, p < 0.001), lower albumin levels (2.7 g/dL vs. 3.2 g/dL, p < 0.001), and greater incidence of lymphopenia (<1000/mcl) (80.3% vs. 46.5%, p < 0.001)." (PMID 32915907, 2020). "Neutrophilia; monocytosis; lymphopenia; elevated NLR, MLR, PLR, and CA-125 levels; and decreased albumin levels were associated with advanced-stage disease and suboptimal debulking." (PMID 32771026, 2020). "Elevated CRP, ALT, neutrophil, urea, decrease albumin, lymphopenia, and IL-6 were also observed in worsening cases resulting in mortality, indicating progression into critically level with resulting liver and renal function test derangement." (PMID 33456651, 2020). "In our study, more severe relative lymphopenia, lower serum albumin, and lower LDH are significantly correlated with higher chance of second‐line immunosuppression use." (PMID 31286682, 2019). "Average OPNI was 38.8 ± 8.2 and significantly lower in patients with: CD type B3; lymphopenia; decreased haemoglobin, prealbumin, and albumin; and daily enteral nutrition <500 kcal/d." (PMID 28814767, 2017).
lymphopenia (continued). "In univariate analysis, the factors that influenced the sensitivity of T-SPOT.TB according to age were lymphopenia, serum protein (or serum albumin), CRP, and being immunocompromised." (PMID 27258377, 2016). "The primary laboratory abnormalities on admission were lymphocytopenia (81.0%), decreased serum albumin (83.3%), and elevated C-reactive protein (CRP) (90.0%), lactate dehydrogenase (LDH) (85.7%), creatine kinase (CK) (84.6%) and AST (73.3%)." (PMID 24595034, 2014). "Simultaneous laboratory findings showed severe hypoproteinemia (total protein 4.5 g/dl, albumin 2.1 g/dl) and lymphopenia (white cell count 3000/μl, lymphocyte count 150/μl)." (PMID 22773935, 2012). "Lymphopenia, low serum albumin level, high CRP level, and the classification into UNKTL or EUNKTL were statistically linked to OS or PFS." (PMID 22682004, 2012). "At that time, hypoproteinemia and lymphopenia improved (total protein 7.2 g/dl, albumin 4.2 g/dl, white cell count 6300/μl, lymphocyte count 2010/μl)." (PMID 22773935, 2012). "Lymphopenia and low serum albumin levels were identified as 2 new independent markers of prognosis in patients with CUP." (PMID 21176210, 2010). "Univariable logistic regression analysis revealed that age, the number of organs involved, SOFA score, APACHE‐II score, hemoglobin, albumin, NT‐proBNP, CD4+T lymphocytes, and persistent lymphocytopenia were risk factors for mortality in MODS patients (p < 0.1)." (PMID 39953665, 2025). "Viruses infect lymphocytes and increase their destruction, causing lymphopenia and a decrease in serum albumin, which is a negative acute-phase reactant, while inducing an increase in CRP and ferritin levels, which are positive acute-phase reactants." (PMID 36788868, 2023). "We first showed that albumin level during CRT can predict delayed lymphopenia after CRT." (PMID 36059659, 2022). "On these bases, our findings on the reduction of both S1P and albumin in serum from COVID‐19 patients might have implications on COVID‐19 lymphopenia, and related immunosuppressive features." (PMID 33190411, 2021). "Worse OS was associated with high mean thoracic RT dose, high CRP/Albumin, large tumor volume and corticosteroids use (p < 0.05, univariate analysis), but not with lymphopenia ≥ G3." (PMID 32181373, 2020). "PJP was independently associated with antilymphocyte monoclonal antibodies (OR 11.47, CI 1.50–87.74), high-dose steroid treatment (OR 4.39, CI 1.52–12.63), lymphopenia (OR 8.13, CI 2.48–26.60), low albumin (OR 0.15, CI 0.40–0.54) and low BMI (OR 0.80, CI 0.68–0.93)." (PMID 32915907, 2020). "Previous studies of severe cases had reported normal/or increased white blood cell count, leucopoenia, lymphopenia, increased haemoglobin level, decreased albumin, increased lactase dehydrogenase, increase CRP, increase D-dimer, aspartate aminotransferase (AST) and alanine aminotransferase (ALT)." (PMID 33456651, 2020). "Age, viral load, lung injury score, and albumin, CRP, LDH, LYM (%), LYM, and NEU (%), may be predictors of disease severity, and lymphopenia is linked to the increased severity, mortality and dysregulated immunological response." (PMID 32746805, 2020). "A study investigated how lymphopenia and low serum albumin could predict prognosis of patients with carcinoma of unknown primary (CUP)." (PMID 21176210, 2010). "In the terminal phase, FIV-infected cats may exhibit immunosuppression signs, including recurrent or chronic infections, neurological signs, lymphoma, mild to moderate anemia, lymphopenia, neutropenia, hypergammaglobulinemia, and a decreased albumin-to-globulin ratio." (PMID 40877940, 2025). "Some viruses infect lymphocytes and by increasing their destruction, it causes lymphopenia and a decrease in serum albumin, which is a negative acute-phase reactant, while it causes an increase in the levels of CRP and ferritin, which are positive acute-phase reactants." (PMID 40956850, 2025).